ANXA1 (annexin A1)
Diseases named in the same sentence as ANXA1 in open-access papers (continued):
Sharing a sentence is not in itself a finding about the gene and the disease.
Insulin resistance (12 papers, 2013 to 2024). Increased resistance towards insulin, that is, diminished effectiveness of insulin in reducing blood glucose levels. "This is even more remarkable when considering that ANXA1 KO mice developed increased adiposity and insulin resistance in response to HFD, which should have been associated with heightened inflammation." (PMID 24312665, 2013). "While female Balb/c mice are resistant to DIO and the associated insulin resistance, we demonstrate that deficiency of a single protein, ANXA1, significantly alters the metabolic profile of this strain towards augmented susceptibility to weight gain." (PMID 24312665, 2013). "AnxA1 deficiency was also detrimental in epithelial wound repair, lung fibrosis, obesity and insulin resistance, skin grafting, bacterial infection, as well as adrenal steroidogenesis in sepsis, or allergic conjunctivitis, and seems to have regulatory functions in early pregnancy." (PMID 33810523, 2021). "Compared with their control littermates, HFD-Anxa1AKO mice exhibited glucose intolerance and insulin resistance, implying that ANXA1 was also essential for glucose regulation and for influencing insulin sensitivity in peripheral tissues." (PMID 39174522, 2024). "Endogenous ANXA1 influenced the passive mechanics of the mesenteric artery in the context of insulin resistance, with its absence worsening the pathological remodeling of blood vessels in insulin-resistant mice." (PMID 39085321, 2024). "Treatment of HFD-fed wildtype mice with recombinant AnxA1 attenuated the development of insulin resistance." (PMID 33810523, 2021). "What, then, is the mechanism(s) by which ANXA1 attenuates insulin resistance in experimental T2D and protects against the development of secondary complications?" (PMID 30972066, 2019). "The saturated fatty acid palmitate, which is elevated in the plasma of obese patients, induced insulin resistance and suppressed AnxA1 expression in L6 myotubes." (PMID 31337068, 2019). "In conclusion, we report here for the first time that mice fed a HFD develop insulin resistance, while endogenous ANXA1 dampens the development of both the diabetic phenotype and the associated hepatic steatosis and nephropathy (proteinuria)." (PMID 30972066, 2019). "In murine diabetic tissues, expression of ANXA1 is decreased allowing for the activation of RhoA, while treatment with hrANXA1 inhibits RhoA activity, decreases insulin resistance, and restores Akt and eNOS signaling." (PMID 30972066, 2019). "A significant increase in fasting glucose and insulin levels as well as development of insulin resistance was observed in ANXA1 KO mice on HFD compared to WT mice." (PMID 24312665, 2013). "Overall, these data indicate the presence of deregulated glucose metabolism and insulin resistance in ANXA1 KO mice on HFD." (PMID 24312665, 2013). "Additionally, research on ANXA1-deficient mice showed that the absence of this protein exacerbates the diabetic phenotype, including dyslipidemia and insulin resistance, indicating a crucial role for ANXA1 in regulating these processes." (PMID 39085321, 2024). "ANXA1 is related to weight gain and diet-induced insulin resistance." (PMID 37293508, 2023). "Hence, as older subjects more often suffer from insulin resistance and cardiovascular disease, these findings further support a function of AnxA1 in metabolic health." (PMID 31337068, 2019). "However, ANXA1 is also upregulated in leukocytes after a glucose load or exposure to TNFα, which induces insulin resistance." (PMID 24312665, 2013). "In the present study, we use a translational approach to gain a better insight into the role of ANXA1 in (a) patients with T2D and (b) a murine model of high fat diet (HFD) induced insulin resistance." (PMID 30972066, 2019). "At variance with WT mice, ANXA1 KO mice on HFD developed significant, although mild, fasting hyperglycemia and hyperinsulinemia – coupled with insulin resistance and glucose intolerance." (PMID 24312665, 2013).
Insulin resistance (continued). "Indeed, cleaved AnxA1 was more abundant in adipose tissues of obese individuals independent of their insulin resistance status." (PMID 31337068, 2019). "Since insulin resistance only occurred in ANXA1 KO mice on HFD but not on chow, it is likely this phenotype was secondary to increased adiposity rather than being independently caused by ANXA1 deficiency." (PMID 24312665, 2013).
lung adenocarcinoma (12 papers, 2012 to 2025). A carcinoma that arises from the lung and is characterized by the presence of malignant glandular epithelial cells. "The overexpression of ANXA1 was observed in H1650 and H1975 lung adenocarcinoma cells with EGFR mutations (H1650: exon 19 deletion; H1975: L858R + T790M) and A549 lung adenocarcinoma cells wild-type EGFR gene." (PMID 34439260, 2021). "The aim of this investigation is to explore the characteristics of expression of Annexin A1 in lung adenocarcinoma A549 cells after hypoxia." (PMID 22613333, 2012). "Furthermore, the expression levels of ANXA1, VEGFC, PDGFC and LRRN3 were significantly positively associated with the survival of lung adenocarcinoma." (PMID 33293474, 2020). "On the other hand, overexpression has been reported in colorectal adenocarcinoma, urothelial carcinoma, lung adenocarcinoma, and oral cancers, thus suggesting that changes in the expression levels of ANXA1 may be related to the tissue or tumor type." (PMID 23431236, 2013). "Hypoxia upregulates the expression of Annexin A1 in lung adenocarcinoma A549 cells, in which process ROS-NF-κB may paticipate in." (PMID 22613333, 2012).
ovarian carcinoma (12 papers, 2012 to 2025). A malignant neoplasm originating from the surface ovarian epithelium. "Subsequently, ANXA1 was found to be indeed associated with drug resistance in ovarian cancer." (PMID 39712859, 2025). "The results indicated that the expression level of ANXA1 was closely related with chemo‐resistance in ovarian cancer cells, which were low expression in parental cells and high expression in drug‐resistant cells." (PMID 39712859, 2025). "Studies have found that the expression of ANXA1 is downregulated in ovarian cancer, and the overexpression of ANXA1 is an independent predictor of prolonged overall survival (OS) in ovarian cancer patients." (PMID 41497316, 2025). "Researchers have found that upregulated ANXA1 is involved in the paclitaxel resistance in ovarian cancer cells." (PMID 32226772, 2020). "For example, disruption of the annexin A1/S100-A11 complex enhanced the migration and clonogenic growth of ovarian cancer cells by modulating epithelial growth factor signaling." (PMID 31545917, 2019). "The results indicate that ANXA1 may be playing an important role in drug resistance in ovarian cancer and that the administered combinations have been able to overcome associated mechanism of resistance." (PMID 27566066, 2016). "Therefore, ANXA1‐mediated cisplatin resistance is reversed in ovarian cancer cells." (PMID 39712859, 2025). "Interestingly, ANXA1 overexpression in epithelial ovarian cancer was shown to be a marker of better overall survival and it has been suggested that this may prove useful in determining what treatment strategies are put in place." (PMID 35146757, 2022). "Thus, the increased expression of Annexin A1 supports the notion that PAX2 may promote tumor growth in TOV21G ovarian cancer cell line by inhibiting the early stages of apoptosis through down-regulation of Annexin A1." (PMID 23502471, 2013). "Ac2‐26 can activate FPR and promote ovarian cancer cell proliferation and MRP1 expression, which is consistent with the high expression of ANXA1 in SKOV3/DDP that we detected." (PMID 39712859, 2025). "ANXA3 was upregulated in platinum-resistant ovarian cancer, whereas ANXA1 and ANXA11 expression was negatively correlated with paclitaxel and cisplatin resistance in ovarian cancer, respectively." (PMID 31474227, 2019). "In addition, the expression levels of ANXA1, ANXA4, ANXA5, ANXA6, ANXA7 and ANXA13 were lower in ovarian cancer than in the normal controls." (PMID 31474227, 2019). "To identify relationship between expression of ANXA1 and chemo‐resistance in ovarian cancer, we examined the difference in the expression of ANXA1 in SKOV3 and SKOV3/DDP cell lines, and the PCR and Western blotting results showed that the expression of ANXA1 in SKOV3/DDP was increased." (PMID 39712859, 2025). "This is in contrast to the suggested role of ANXA1 in this form of ovarian cancer, suggesting the signalling of ANXA1 in this process may not be predominantly mediated through FPR2." (PMID 35146757, 2022). "Secondly, the survival analyses of patients with ovarian cancer clearly indicated that the expression levels of CALR, PDIA3, ANXA1, HMGB1, IFNAR1, and PANX1 had no significant influence on overall survival (OS) and disease-free survival (DFS)." (PMID 35991556, 2022). "Firstly, the expression analyses of patients with ovarian cancer showed that the expression levels of CALR and PDIA3 in ovarian cancer were significantly up-regulated in compared with normal control tissues, while the expression of PANX1, ANXA1, HMGB1, and IFNAR1 were nonsignificant." (PMID 35991556, 2022).
uveitis (12 papers, 2011 to 2025). An inflammatory process affecting a part of or the entire uvea. "Treatment with the ANXA1-derived mimetic peptide, Ac2-26, in models of endotoxin-induced uveitis, reduces leukocyte infiltration and the release of inflammatory mediators, including IL-1β." (PMID 41200163, 2025). "In diseases such as conjunctivitis, uveitis, peritonitis, and pneumonia, annexin A1 or Ac2-26 reduces neutrophil recruitment." (PMID 39768195, 2024). "The authors observed that retinal expression of AnxA1 increased during uveitis compared with healthy controls." (PMID 35562891, 2022). "Some authors have also examined the expression of the anti-inflammatory protein AnxA1 in mice and the human retina during uveitis." (PMID 35562891, 2022). "Concerning the uveitis, the expression of AnxA1 in leukocytes and aqueous humor (AqH) was observed in endotoxin-induced uveitis (EIU) in rats, with this protein noted as one of the essential mediators in the inflammatory homeostasis process." (PMID 34831393, 2021). "Data obtained after systemic treatments with Ac2-26 and PL in EIU confirmed the anti-inflammatory action of AnxA1 mimetic peptide in experimental ocular inflammation, including uveitis, as previously reported by our research group." (PMID 34831393, 2021). "We investigated the effects of piperlongumine (PL) and/or annexin A1 (AnxA1) mimetic peptide Ac2-26 on endotoxin-induced uveitis (EIU)." (PMID 34831393, 2021). "This study strengthened the role of tear proteomics as potential sources of biomarkers for uveitis and established α1-AGP and ANXA1 as potential biomarkers for monitoring of uveitis in BD." (PMID 33343583, 2020). "The decrease of ANXA1 in tears from BDU possibly implies loss of inflammation homeostasis and an actively-inflammed status in active uveitis." (PMID 32596040, 2020). "The statistical analysis showed significantly higher Anxa1 expression in neutrophils and mononuclear phagocytes at 48 h than at 24 h after uveitis induction." (PMID 21633711, 2011). "Beyond, Annexin A1 and its fragment Ac2-26 have demonstrated positive effects in various preclinical models of pathological conditions, such as multiple sclerosis, pneumococcal pneumonia, arthritis, uveitis, and wound healing." (PMID 39768195, 2024). "In addition, previous studies reported that ANXA1 (Ac2-26) inhibits inflammatory responses through Fpr2 in LPS-induced uveitis in rats." (PMID 36544058, 2023). "The immunohistochemical and densitometric analyses of AnxA1 expression in the anterior eye segment showed significant increase in the endogenous protein, especially in the ciliary processes, 24 h after uveitis induction in the untreated group (p < 0.001) compared to the control." (PMID 34831393, 2021). "In particular, the endogenous protein annexin A1 (AnxA1) may represent an alternative therapy for uveitis." (PMID 34831393, 2021). "Therefore tear proteins such as α1-AGP and ANXA1 were promising tear biomarkers for uveitis monitoring." (PMID 32596040, 2020). "Reinforcing the involvement of AnxA1 pathway in neutrophil recruitment, AnxA1-null mice demonstrated a higher extent of neutrophil extravasation in animal models of peritonitis, allergic conjunctivitis, and uveitis." (PMID 26885535, 2016). "However, in animals pretreated with c48/80 and evaluated 24 h after uveitis induction, an increased immunoreactivity for Anxa1 was detected when compared with other experimental groups." (PMID 21633711, 2011). "ANXA1 promotes Th1 differentiation by upregulating T-bet and IFN-γ, whereas its effects on Th17 cells involve restricting IL-17 in Th17-associated diseases such as uveitis, yet promoting Th17 accumulation in other conditions like experimental autoimmune encephalomyelitis." (PMID 40977888, 2025). "Thus, Anxa1 may be an innovative form of therapy for uveitis, by preventing the activation of mast cells and/or the infiltration of leukocytes in ocular tissues." (PMID 21633711, 2011).
uveitis (continued). "It has been shown that ANXA1 (Ac2-26) reduces the production of proinflammatory cytokines, such as TNF-α, IL-1β and IL-6, in LPS-induced uveitis." (PMID 36544058, 2023). "In the absence of AnxA1, the inflammatory response is exacerbated as demonstrated by increased neutrophil extravasation following zymosan-induced peritonitis and endotoxin-induced uveitis." (PMID 26885535, 2016).
breast tumors (11 papers, 2012 to 2024). "We found that Annexin A1 expression correlated with poor patient prognosis in basal-like breast tumors and also in the basal like-2 subset of TNBCs." (PMID 33800279, 2021). "Annexin A1 mRNA levels correlated with poor patient prognosis in basal-like breast tumors and also in the basal-like 2 subset of TNBCs." (PMID 33800279, 2021). "To further understand the timing of anxA1 expression in intratumoral vessels, we undertook a time course IHC study in the Py230 orthotopic breast tumor and B16-F10-Luc2 lung metastatic models." (PMID 32497150, 2020). "Targeted inhibition of ANXA1 can reduce the function of Tregs and shrink breast tumors." (PMID 33790966, 2021). "Breast tumors with low levels of the ANXA1 displayed a benefit from trastuzumab." (PMID 29416786, 2018). "ANXA1 binds to cell membrane phospholipids and can be phosphorylated by the epidermal growth factor receptor, TRPM7 channel kinase 1, protein kinase A and protein kinase C. Its expression has been linked to carcinogenesis and metastasis in various tumor types, including breast tumors." (PMID 39040439, 2024). "While those of ANXA1 were not significantly different between ER+- and ER--breast tumor tissue, they were significantly lower in both ER+- and ER--breast tumor tissues than in their corresponding tumor-adjacent tissues." (PMID 29416786, 2018). "Throughout the tumor areas of the Py230 orthotopic breast tumor model, the walls of neovessels were strongly positive (2–3+) for anxA1 staining by endpoint day 44; however, the signal was localized to the vascular smooth-muscle cells, and the subjacent endothelial cells were negative for anxA1." (PMID 32497150, 2020).
head and neck cancer (11 papers, 2013 to 2023). A primary or metastatic malignant neoplasm affecting the head and neck. "The expression of annexin A1 is associated with advanced stage of the disease, metastasis and differentiation status in head and neck cancers." (PMID 37580662, 2023). "Downregulation of ANXA1 has also been associated with radiotherapy resistance and increased relapse rates in head and neck cancer." (PMID 29868478, 2018). "Reduced expression levels of ANXA1 have so far been described in several types of tumors including breast and head and neck cancers." (PMID 35454784, 2022). "For example, ANXA1 has tumor suppressor roles in prostate, oral squamous cell and head and neck cancer." (PMID 34439260, 2021). "This is the first direct evidence of annexin A1 overexpression in lymph node metastasis of head and neck cancer." (PMID 30157864, 2018). "ANXA1 has been reported to have an anti-proliferative effect mediated by the intracellular form of the protein, and it has been found that both mRNA and protein levels are down-regulated in head and neck cancer tissues." (PMID 32742772, 2020). "Despite methodological limitations, this study provides, for the first time, direct evidence of annexin A1 overexpression in lymph node metastasis of head and neck cancer and adds information that may be useful for diagnosing metastatic disease." (PMID 30157864, 2018). "Our study, for the first time, provided direct evidence of annexin A1 overexpression in lymph node metastasis of head and neck cancer, adding information that may be useful for diagnosing aggressive disease." (PMID 30157864, 2018). "Although there is still controversy regarding Annexin A1 expression in different types of cancers, including breast, pancreatic, hepatic, prostate, urothelial, cervical, and head and neck cancer, low Annexin A1 expression correlates with poor pathologic differentiation grade." (PMID 23786757, 2013).
ischemia (11 papers, 2013 to 2025). A hypoperfusion of the BLOOD through an organ or tissue caused by a PATHOLOGIC CONSTRICTION or obstruction of its BLOOD VESSELS, or an absence of BLOOD CIRCULATION. "The main finding is that 10 genes (Clec5a, CD14, Fgr, Hck, Anxa1, Lgals3, Irf1, Lbp, Ptx3, Serping1) may represent key molecular links underlying acute activation of immune cells in the hippocampus in response to experimental ischemia." (PMID 34944656, 2021). "Our novel findings show that AnxA1 was able to increase blood flow cessation after a subsequent thrombotic event postcerebral ischemia, thereby showing the diverse nature of AnxA1." (PMID 31154815, 2019). "Several lines of evidence have demonstrated a neuroprotective effect of ANXA1 in ischemia as well as microglial migration to sites of injury where they can release chemokines and carry out phagocytosis." (PMID 27782092, 2016). "Conversely, the overexpression of endothelial CYP2J2 preserves the distribution of endothelial tight junctions and adherens junctions in an ANXA1-dependent manner, thus safeguarding the integrity of the BRB and shielding retinal ganglion cells from loss following ischemia-reperfusion injury." (PMID 40276708, 2025). "In addition, Tat-NTS peptide also upregulated ANXA1 SUMOylation in mouse microglia, which was reduced by ischemia." (PMID 37908731, 2023). "These combined findings underline the importance of ANXA1 as a neuroprotective agent in maintaining BBB integrity in the context of neonatal hypoxic-ischemia and ANXA1 driven stabilization of laminin expression in the neurovascular unit as an essential mechanism herein." (PMID 36983004, 2023). "Considering that ANXA1 depletion occurs within the first 72 h upon ischemia in cerebrovasculature and ependyma, supplementation of exogenous ANXA1 should be conducted within the pharmacological window of opportunity of at most three days after the HI insult, but preferably earlier." (PMID 30682787, 2019). "Experiments on mouse had shown that ANXA1 plays a protective role in ischemia." (PMID 27782092, 2016). "As expected, administration of Tat-NTS peptide alone, or administration of Tat-NTS peptide under the premise of overexpression of ANXA1-WT, or only overexpression of ANXA1-SUMO2 in microglia of model mice, can greatly protect against ischemia-induced neurological impairment." (PMID 37908731, 2023). "Consistent with previous reports that hippocampal CA1 is more sensitive to ischemia than the DG or CA3, we found that changes in microglial activation and ANXA1 expression were not significant in CA3 or DG after OGD/R treatment." (PMID 27782092, 2016).